TMEM232 (transmembrane protein 232)
Description:
Plays a critical role for male fertility and sperm motility by regulating sperm cytoplasm removal and maintaining axoneme integrity.
Synonyms: FLJ43080
Tractability: Antibody: UniProt predicts a signal peptide or a membrane-spanning region.
Gene: Protein-coding gene on chromosome 5 (110,289,233 to 110,738,956, reverse strand). Ensembl gene ENSG00000186952.
Subcellular location: Membrane
Gene Ontology:
Biological process: flagellated sperm motility; spermatid cytoplasm removal during spermiation of flagellated sperm; spermatogenesis
Cellular component: outer dense fiber; membrane
Genetic constraint (gnomAD): Loss-of-function variants: 65 observed, 61.47 expected, observed/expected ratio (o/e) 1.06, 90% interval 0.87 to 1.3. The upper end of that interval is the gene's LOEUF score, 1.3, which puts it in group 5 of 6, group 1 being the genes least tolerant of losing a copy. Missense variants: 720 observed, 619.39 expected, observed/expected ratio (o/e) 1.16, 90% interval 1.09 to 1.24. Synonymous variants: 252 observed, 217.37 expected, observed/expected ratio (o/e) 1.16, 90% interval 1.04 to 1.29.
Homologues: Orthologues: chimpanzee TMEM232 (99% identical), macaque TMEM232 (95% identical), dog TMEM232 (77% identical), pig TMEM232 (72% identical), rabbit TMEM232 (70% identical), mouse Tmem232 (66% identical), rat Tmem232 (65% identical), guinea pig TMEM232 (60% identical), tropical clawed frog tmem232 (36% identical), zebrafish tmem232 (29% identical).
Diseases named in the same sentence as TMEM232 in open-access papers:
TMEM232 is named in the same sentence as 14 diseases in open-access papers, as found by Europe PMC text mining. Sharing a sentence is not in itself a finding about the gene and the disease. The quoted sentences say what the papers report.
atopic dermatitis (5 papers, 2019 to 2026). "Genetic variants in TMEM232 have been associated with atopic dermatitis and allergic rhinitis in GWAS36,37." (PMID 31064978, 2019). "The second most significant promoter-associated DMR is located in the TMEM232 gene, which encodes a transmembrane protein that promotes inflammatory responses to atopic dermatitis, and has been implicated by genetic studies in allergic and atopic diseases characterized by immune dysregulation." (PMID 41542061, 2026). "Furthermore, TMEM232 has been reported as a susceptibility gene for atopic dermatitis in the Chinese Han population, which was also confirmed in the Japanese and Korean populations." (PMID 39516485, 2024). "While the function of TMEM232 is still unknown, variants in this gene have been associated with atopic dermatitis and allergic rhinitis in GWAS36,37." (PMID 31064978, 2019). "To investigate the role of TMEM232 in atopic dermatitis, we generated Tmem232 knockout (KO) mice." (PMID 39516485, 2024).
allergic rhinitis (3 papers, 2019 to 2024). Inflammation of the nasal mucous membranes caused by an IgE-mediated response to external allergens. "A study on European participants confirmed an association between TMEM232 and allergic rhinitis." (PMID 39596646, 2024). "TMEM232 has previously been associated with respiratory traits, such as seasonal allergic rhinitis." (PMID 34775485, 2022). "SLC30A8 has been implied in blood sugar levels and TMEM232 in allergic rhinitis and asthma." (PMID 34775485, 2022).
asthma (3 papers, 2022 to 2024). "TMEM232 has been confirmed to be associated with childhood food allergies and asthma." (PMID 39596646, 2024). "The transmembrane protein 232 (TMEM232) gene has been associated with lung diseases such as asthma." (PMID 37606455, 2023).
male infertility (3 papers, 2023 to 2024). The inability of the male to effect fertilization of an ovum after a specified period of unprotected intercourse. "Owing to the essential role of TMEM232 during spermatogenesis, TMEM232-deficient mice exhibited abnormal sperm phenotypes, and insufficient energy supply, resulting in male infertility." (PMID 39516485, 2024). "Damage in the integrity of microtubule doublet structure has been shown to be associated with sperm motility defects and male infertility, as seen for the deletion of Ccdc176, Tmem232, Cfap97d1, Dnah17, Trll9, Pla2g3 and Vdac3 in mice." (PMID 38750428, 2024). "Our findings provide a better understanding of the function of TMEM232 in sperm formation, advancing the knowledge of male infertility." (PMID 39516485, 2024). "Collectively, these data indicate that TMEM232 is involved in sperm flagellar motility and that its abnormality may further lead to male infertility." (PMID 39516485, 2024).
Infertility (2 papers, 2023 to 2024). "Our study provided the phenotypic identification and molecular dissection of mouse infertility caused by Tmem232 deficiency." (PMID 39516485, 2024). "Phenotypic analysis showed that deletion of Tmem232 in mice causes male-specific infertility." (PMID 37371084, 2023). "Studying the mechanism of Tmem232 may provide a promising therapeutic target for future infertility research." (PMID 37371084, 2023). "Here, we show that the lack of Tmem232 leads to the deletion of the fourth doublet microtubule, a midpiece-principal piece junction defect, and irregular MS arrangement in sperm, which finally cause infertility." (PMID 39516485, 2024).
allergic disease (1 paper, 2024). An immune response that occurs following re-exposure to an innocuous antigen, and that requires the presence of existing antibodies against that antigen. "A GWAS conducted at the UK Biobank Europeans confirmed the association of TMEM232 with allergic diseases, immunoglobulin type E in grass, and AD." (PMID 39596646, 2024). "Infants carrying the wild-type allele C of TMEM232 rs17132261 showed an increased risk of AD and higher total IgE levels due to maternal factors such as susceptibility to allergic diseases compared with those carrying the T allele." (PMID 39596646, 2024). "In conclusion, this study reports that the TMEM232 gene in cord blood is associated with infant total IgE, which is important in normal immune responses and preventing allergic diseases." (PMID 39596646, 2024). "In this study, we confirmed the association between infant AD and the TMEM232 variant rs17132261, which is mediated by a maternal history of allergic disease and sensitization to Der f." (PMID 39596646, 2024). "TMEM232 has also been implicated in the development of several allergic diseases, the underlying mechanisms of which are thought to involve blood components." (PMID 39596646, 2024). "Therefore, the risk of AD in infants increases when mothers have a history of allergic diseases or are sensitized to Der f, particularly with a presence of TMEM232 rs17132261 C alleles." (PMID 39596646, 2024). "Additionally, some Asian populations, including Chinese and Japanese populations, are especially susceptible to allergic diseases owing to variations in TMEM232." (PMID 39596646, 2024). "We observed significant differences in total IgE and monocyte levels after adjusting for maternal age and feeding method in relation to children’s AD risk factors, including the TMEM232 C allele, maternal history of allergic diseases, and sensitization to Der f." (PMID 39596646, 2024). "Genetic variants of TMEM232 are associated with several allergic diseases, including AD." (PMID 39596646, 2024). "Moreover, the TMEM232 variant rs17132261 may be implicated in the maternal history of allergic disease and sensitization to the Der f-mediated pathogenesis of AD and other allergic diseases." (PMID 39596646, 2024). "TMEM232 was confirmed to be related to AD as a genetic factor, and a correlation showed that maternal history of allergic disease and sensitization to Der f." (PMID 39596646, 2024). "We compared the children’s blood biomarkers considering the TMEM232 genotype alongside maternal history of allergic diseases and sensitization to Der f." (PMID 39596646, 2024).
asthenozoospermia (1 paper, 2024). "Our findings provide comprehensive experimental evidence for the function and important role of TMEM232 in sperm motility and flagellum development and highlight the pathological basis of asthenozoospermia, with implications for its clinical diagnosis and treatment." (PMID 39516485, 2024). "Interestingly, the Tmem232 KO mice were infertile and had a typical phenotype of asthenozoospermia." (PMID 39516485, 2024).
Azoospermia (1 paper, 2023). Absence of any measurable level of sperm,whereby spermatozoa cannot be observed even after centrifugation of the semen pellet. "As a conserved gene, Tmem232 has the potential to be a pathogenic gene in clinical azoospermia." (PMID 37371084, 2023).
multiple sclerosis (1 paper, 2022). A progressive autoimmune disorder affecting the central nervous system resulting in demyelination. "A further four—ATP9A, TMEM232, PHACTR2 and SLC6A11—out of the seven autoimmune genes identified in this study can also be linked to multiple sclerosis development." (PMID 36517845, 2022).
cancer (1 paper, 2022). A tumor composed of atypical neoplastic, often pleomorphic cells that invade other tissues. "In our model, the TMEM232 expression pattern was similar to ADAM28, with higher expression in low-risk cancers." (PMID 35806060, 2022). "Proteins of this family have differential expression in cancers, but there is limited information on TMEM232." (PMID 35806060, 2022). "Some of them require more detailed studies since their biological role, especially in cancer, is unknown, or the data are contradictory (ADAM28, TMEM232, DPY19L3-DT, and E9PMD0)." (PMID 35806060, 2022).
TMEM232 also shares sentences with these, for which no sentence is quoted: food allergies (1 paper); hyperglycaemia (1); Insulin resistance (1); lung diseases (1).